HNRNPAB (heterogeneous nuclear ribonucleoprotein A/B)
Description:
Binds single-stranded RNA. Has a high affinity for G-rich and U-rich regions of hnRNA. Also binds to APOB mRNA transcripts around the RNA editing site.
Synonyms: ABBP1; HNRPAB; FLJ40338
Tractability: PROTAC: UniProt records ubiquitination sites on it; ubiquitination databases record sites on it; its protein half-life has been measured.
Target class: Other nuclear protein
Gene: Protein-coding gene on chromosome 5 (178,204,479 to 178,211,183, forward strand). Ensembl gene ENSG00000197451.
Subcellular location: Nucleus; Cytoplasm
Subcellular location (Human Protein Atlas): Nucleoplasm
Gene Ontology:
Molecular function: protein binding; RNA binding; mRNA binding; nucleic acid binding; protein-containing complex binding; sequence-specific double-stranded DNA binding
Biological process: mRNA modification; negative regulation of nuclear-transcribed mRNA catabolic process, nonsense-mediated decay; chromosomal 5-methylcytosine DNA demethylation pathway; epithelial to mesenchymal transition; positive regulation of DNA-templated transcription; regulation of gene expression; cellular response to amino acid stimulus; regulation of cellular localization; regulation of intracellular mRNA localization
Cellular component: nucleoplasm; nucleus; ribonucleoprotein complex; chromatin; cytoplasm; mRNA editing complex; RNA polymerase II transcription regulator complex; dendrite; neuronal ribonucleoprotein granule; protein-containing complex
Genetic constraint (gnomAD): Loss-of-function variants: 17 observed, 42.27 expected, observed/expected ratio (o/e) 0.4, 90% interval 0.27 to 0.6. The upper end of that interval is the gene's LOEUF score, 0.6, which puts it in group 2 of 6, group 1 being the genes least tolerant of losing a copy. Missense variants: 393 observed, 412.48 expected, observed/expected ratio (o/e) 0.95, 90% interval 0.88 to 1.04. Synonymous variants: 183 observed, 161.25 expected, observed/expected ratio (o/e) 1.13, 90% interval 1 to 1.28.
Homologues: Orthologues: chimpanzee HNRNPAB (99% identical), macaque HNRNPAB (99% identical), dog HNRNPAB (97% identical), guinea pig HNRNPAB (95% identical), rat Hnrnpab (93% identical), mouse Hnrnpab (92% identical), tropical clawed frog hnrnpab (76% identical), zebrafish hnrnpaba (71% identical), zebrafish hnrnpabb (69% identical), rabbit HNRNPAB (66% identical). Paralogues in human: HNRNPD (64% identical), HNRNPDL (58% identical), MSI2 (33% identical), HNRNPA3 (33% identical), MSI1 (31% identical), HNRNPA1 (30% identical), HNRNPA2B1 (30% identical), HNRNPA1L3 (29% identical), DAZAP1 (29% identical), HNRNPA1L2 (29% identical), NUCLEOLIN (27% identical), RBM39 (26% identical), and 24 more.
Diseases named in the same sentence as HNRNPAB in open-access papers:
HNRNPAB is named in the same sentence as 23 diseases in open-access papers, as found by Europe PMC text mining. Sharing a sentence is not in itself a finding about the gene and the disease. The quoted sentences say what the papers report.
prostate carcinoma (7 papers, 2020 to 2025). A carcinoma that arises from epithelial cells of the prostate gland. "PCAT19 interacts with HNRNPAB to activate a subset of cell-cycle genes associated with prostate cancer progression, thereby promoting prostate cancer tumor growth and metastasis." (PMID 35095999, 2021). "The lncRNA PCAT19 also interacts with HNRNPAB to activate a subset of cell‐cycle genes associated with prostate cancer progression, thus promoting prostate cancer growth and metastasis." (PMID 32364285, 2020). "For instance, only the long isoform AS of lncRNA prostate cancer-associated transcript 19 (PCAT19) promotes prostate cancer growth and metastasis by interacting with the heterogeneous nuclear ribonucleoprotein A/B (HNRNPAB) complex, in contrast to its short isoform." (PMID 39724297, 2025). "HNRNPAB interacts with lncRNA-PCAT19 to activate a subset of cell cycle-related genes in the progression of prostate carcinoma." (PMID 32509843, 2020). "Existing studies have suggested that it could interact with HNRNPAB to facilitate the progression and metastasis of prostate cancer." (PMID 35480331, 2022). "PCAT19-long promoted prostate cancer progression by interacting with a nuclear riboprotein, Heterogeneous Nuclear Ribonucleoprotein A/B (HNRNPAB), to upregulate a subset of cell-cycle genes, suggesting a novel mechanism for the HNRNPAB role in prostate cancer progression." (PMID 34946977, 2021).
hepatocellular carcinoma (5 papers, 2016 to 2020). A malignant tumor that arises from hepatocytes. "Previous studies have reported that HNRNPAB overexpression induces epithelial-mesenchymal transition and promotes the metastasis of hepatocellular carcinoma (HCC) via transcriptional regulation of SNAIL and lncRNA-ELF209." (PMID 32509843, 2020). "Besides, HNRNPAB overexpression has been found in metastatic cells or cancer tissues in hepatocellular carcinoma patients, which lead to EMT and metastasis of hepatocellular carcinoma cells in vivo." (PMID 32915499, 2020). "In human hepatocellular carcinoma (HCC) cells, heterogeneous nuclear ribonucleoprotein AB (HNRNPAB) overexpression promotes cell migration and invasion through transcriptional activation of Snail1." (PMID 27705942, 2016).
breast carcinoma (3 papers, 2020 to 2026). "Elevated expression of HNRNPAB was positively associated with more aggressive diseases and poorer survival rates in breast cancer." (PMID 37920509, 2023). "HNRNPAB promoted the back-splicing and expression of circESR1 by binding to the Alu elements of cognate pre-mRNA; and circESR1 transcripts increased the stability and expression of HNRNPAB, ensuring an efficient positive feedback loop as reflected in antiestrogen-resistant breast cancer cells." (PMID 41608617, 2026). "Hence, these findings elucidated a novel signaling complex centered around circESR1 and HNRNPAB in ER+ breast cancer, and suggested that circESR1 might represent a potential therapeutic target for this disease." (PMID 41608617, 2026).
colorectal cancer (2 papers, 2022). A primary or metastatic malignant neoplasm that affects the colon or rectum. "Moreover, we identified some diseases and phenotypes related to HNRNPAB/PLAUR/SEMA3A from the database, including non-small cell lung carcinoma (NSCLC), colorectal carcinoma (CRC) and LUAD (disorder)." (PMID 36091160, 2022).
liver cancer (2 papers, 2020 to 2022). An epithelial or non-epithelial malignant neoplasm that arises from the liver. "In addition, upregulation of typical splicing proteins such as SRSF2, hnRNPL, hnRNPA2, hnRNPA2B1 and hnRNPAB were previously observed in liver cancers 33-37, although their misregulated splicing events have not been fully identified." (PMID 32483414, 2020).
lung cancer (2 papers, 2017 to 2022). A malignant neoplasm involving the lung. "Expression of HNRNPAB was found to be up-regulated in lung cancer tissues compared with the cancer adjacent tissues." (PMID 36091160, 2022). "In addition, we found plant-derived traditional Chinese medicine components targeting both HNRNPAB and SEMA3A, including 17 beta-estradiol, a natural compound exhibiting broad anti-cancer effects against lung cancer." (PMID 36091160, 2022). "IHC staining also confirmed that HNRNPAB, PLAUR, and SEMA3A protein expressions in lung cancer specimens were significantly increased, which supported our hypothesis." (PMID 36091160, 2022). "However, the expression pattern of HNRNPAB in lung cancer have not been reported." (PMID 36091160, 2022).
cortical atrophy (1 paper, 2025). "The higher abundance of HNRNPAB in SD (and FTLD-TAU), with no changes in AD and NDC, was positively related to degree of cortical atrophy." (PMID 40713859, 2025).
lung adenocarcinoma (1 paper, 2022). A carcinoma that arises from the lung and is characterized by the presence of malignant glandular epithelial cells. "At the same time, the expressions of HNRNPAB/PLAUR and SEMA3A were detected in the cancer and paracancerous tissues of a lung adenocarcinoma patient, as determined by IHC." (PMID 36091160, 2022). "Furthermore, HNRNPAB/PLAUR and SEMA3A were considered by us as significant predictive target genes of the PTEN-related LINC00460/miR-150-3p axis in lung adenocarcinoma." (PMID 36091160, 2022).
Strabismus (1 paper, 2021). A misalignment of the eyes so that the visual axes deviate from bifoveal fixation. "For probands with HNRNPAB variants, DD/ID is common, as are delayed speech and language, ASD, hypotonia, and strabismus." (PMID 33874999, 2021).
tumor (10 papers, 2008 to 2026). "The oncogenic effect of HNRNPA1 and HNRNPAB is of great interest to understand the underlying mechanisms of alternative splicing in carcinogenesis, which might provide novel insights into anti‐tumour therapy." (PMID 32915499, 2020). "hnRNPAB enhances CXCL8‐dependent neutrophil recruitment by prolonging the half‐life of MYC mRNA in metastatic tumor cells." (PMID 40027151, 2025). "Metastatic tumor cells also exhibit high expression of heterogeneous nuclear ribonucleoprotein AB (hnRNPAB), which stabilizes MYC mRNA and promotes neutrophil recruitment at extravasation sites through the secretion of CXCL8." (PMID 40027151, 2025). "This reduced binding leads to a decrease in the expression of the tumor-suppressing PCAT19-short and an increase in the oncogenic PCAT19-long, promoting cell proliferation and tumor growth through interaction with HNRNPAB." (PMID 38249783, 2024). "According to the MEXPRESS database, the methylation of HNRNPAB/PLAUR/SEMA3A was associated with several clinical factors including ‘new tumour event after initial treatment’ and ‘tumour stage’." (PMID 36091160, 2022). "Subsequently PCAT19-long isoform interacts with HNRNPAB and thus influences expression of cell cycle genes leading to acceleration of tumor growth and metastasis." (PMID 34449663, 2021). "This favors accumulation of the long PCAT19 isoform that interacts with HNRNPAB and promotes the expression of cell cycle genes that subsequently fuel tumor growth and metastasis." (PMID 34449663, 2021). "Heterogeneous distributions of hnRNP genes were observed in different cancer types: HNRNPA1 and HNRNPAB were highly expressed in most tumours." (PMID 32915499, 2020). "HnRNP genes demonstrated heterogeneous distributions in different cancer types: HNRNPA1 and HNRNPAB were highly expressed in most tumours; HNRNPA1P33 expression was increased in COAD, READ and LUAD whereas decreased in CHOL, PRAD and BLCA." (PMID 32915499, 2020). "Summarily, tRF‐22 likely prompts tumor growth through a “hnRNPAB–TGFβ2–PMN‐MDSCs–CD8+ T cell” axis." (PMID 41144758, 2026). "In vivo, tRF‐22 overexpression resulted in tumor growth accompanied by an increase in PMN‐MDSCs and a decrease in CD8+ T cells, while these effects were mitigated by silencing HNRNPAB or TGFB2, or by applying anti‐TGFβ antibody." (PMID 41144758, 2026). "The expression of LINC00460/EME1/HNRNPAB/PLAUR and SEMA3A was higher in most tumour tissues, including LUAD, than in the corresponding control tissues (P < 0.001)." (PMID 36091160, 2022). "The relationship between the abundance of tumour-infiltrating lymphocytes (TILs) and the expression of EME1/HNRNPAB/PLAUR/SEMA3A in pan-cancer and LUAD was demonstrated on heatmaps and lollipop graphs." (PMID 36091160, 2022). "Similarly, DHCR7 (cholesterol biosynthesis), DDIT4 (mTOR regulation under stress), HNRNPAB (RNA splicing), and SLC39A8 (zinc signaling) all reflect well-documented mechanisms of tumor growth or adaptation." (PMID 40941703, 2025). "Furthermore, we analyzed the expression of ceRNAs in tumour and control samples using TCGA, GTEx, and CPTAC databases and found that the expressions of LINC00460/EME1/HNRNPAB/PLAUR/SEMA3A were significantly higher in LUAD tissues." (PMID 36091160, 2022).
cancer (8 papers, 2008 to 2026). A tumor composed of atypical neoplastic, often pleomorphic cells that invade other tissues. "Patients whose cancer exhibited high levels of circESR1 and/or HNRNPAB exhibited advanced prognostic stage and poor survival." (PMID 41608617, 2026). "The GSCA database was used to examine the role of EME1/HNRNPAB/PLAUR/SEMA3A in 10 cancer pathways and found that EME1 was mainly involved in the activation of apoptosis, cell cycle and DNA damage response and inhibition of RAS/MAPK pathways." (PMID 36091160, 2022). "CCLE was used to assess the expression distribution of EME1/HNRNPAB/PLAUR/SEMA3A in pan-cancer cell lines." (PMID 36091160, 2022). "Little is known about hnRNPAB outside of cancer, but it has been shown to regulate expression of neurodevelopmental genes and those involved in glutamate signaling, as well as neural cell motility." (PMID 33874999, 2021). "Potential mechanisms underlying this variability may include tRF‐22 targeting genes or signaling pathways beyond hnRNPAB in other cancer types, as well as its regulation being influenced by co‐expressed regulatory factors or transcriptional variations." (PMID 41144758, 2026). "Even if tRF‐22 interacts with hnRNPAB, its regulation of hnRNPAB's epigenetic modifications, protein abundance, and biological functions may vary across cancer types." (PMID 41144758, 2026). "Next, we visualized the differential expression of HNRNPAB in each cancer." (PMID 32915499, 2020). "However, it is possible that under stress conditions, the UBA2A gene mutation could affect some post‐germination processes, as its human homolog hnRNPAB has been shown to regulate a specific set of processes, including influenza virus replication and cancer cells, malignancy." (PMID 41131965, 2025). "Studies suggested that the completely different evolutionary directions between hnRNPA/B and hnRNPAB might lead to very different biological functions, but this review will not dwell on this but will focus only on the progress of hnRNPA/B family members in cancer." (PMID 35879279, 2022).
hematological malignancies (1 paper, 2020). "Oncomine database analysis further confirmed that HNRNPAB was overexpressed in several solid tumors and hematological malignancies." (PMID 32509843, 2020).
HNRNPAB also shares sentences with these, for which no sentence is quoted: cervical cancer (2 papers); Alzheimer disease (1); amyotrophic lateral sclerosis (1); avian influenza (1); cholangiocarcinoma (1); colitis (1); frontotemporal lobar degeneration (1); lymph node metastasis (1); neurodegenerative disease (1); non-small cell lung carcinoma (1); Parkinson disease (1).